GJC1 (gap junction protein gamma 1)
Description:
Structural component of the gap junction, a specialized intercellular structure consisting of a cluster of closely packed pairs of transmembrane channels, the connexons, that allow passage of small molecules and electrical signals between neighboring cells. Forms homotypic and heterotypic channels gated by transjunctional voltage (By similarity). Involved in intercellular innate immune signaling. Mediates translocation of 2',3'-cGAMP and 2',5'-oligoadenylates (2-5A) second messengers from virus-infected cells to macrophages and uninfected neighboring cells to propagate and amplify the antiviral immune response.
Synonyms: Cx45; GJA7
Tractability: Antibody: its Gene Ontology location is reachable by antibodies, with high confidence; UniProt places it where antibodies can reach, with medium confidence; UniProt predicts a signal peptide or a membrane-spanning region; the Human Protein Atlas places it where antibodies can reach. PROTAC: ubiquitination databases record sites on it.
Gene: Protein-coding gene on chromosome 17 (44,798,448 to 44,831,496, reverse strand). Ensembl gene ENSG00000182963.
Subcellular location: Cell membrane; Cell junction, gap junction
Subcellular location (Human Protein Atlas): Plasma membrane; Endoplasmic reticulum; Nucleoplasm
Pathways (Reactome):
Neuronal System: Electric Transmission Across Gap Junctions
Vesicle-mediated transport: Gap junction assembly
Gene Ontology:
Molecular function: protein binding; gap junction channel activity; gap junction channel activity involved in AV node cell-bundle of His cell electrical coupling; gap junction channel activity involved in SA node cell-atrial cardiac muscle cell electrical coupling; monoatomic ion channel activity
Biological process: atrial cardiac muscle cell action potential; AV node cell to bundle of His cell communication by electrical coupling; cell-cell junction assembly; cell-cell signaling; gap junction assembly; muscle contraction; SA node cell to atrial cardiac muscle cell communication by electrical coupling; cell communication; monoatomic ion transmembrane transport; transmembrane transport
Cellular component: plasma membrane; connexin complex; endoplasmic reticulum membrane; gap junction; intercalated disc
Genetic constraint (gnomAD): Loss-of-function variants: 5 observed, 30.2 expected, observed/expected ratio (o/e) 0.17, 90% interval 0.086 to 0.35. The upper end of that interval is the gene's LOEUF score, 0.35, which puts it in group 1 of 6, group 1 being the genes least tolerant of losing a copy. Missense variants: 308 observed, 519.25 expected, observed/expected ratio (o/e) 0.59, 90% interval 0.54 to 0.65. Synonymous variants: 175 observed, 193.42 expected, observed/expected ratio (o/e) 0.9, 90% interval 0.8 to 1.03.
Homologues: Orthologues: chimpanzee GJC1 (100% identical), macaque GJC1 (99% identical), rabbit GJC1 (97% identical), mouse Gjc1 (97% identical), rat Gjc1 (97% identical), pig GJC1 (97% identical), guinea pig GJC1 (91% identical), dog GJC1 (89% identical), tropical clawed frog gjc1 (72% identical). Paralogues in human: GJC2 (48% identical), GJA3 (32% identical), GJA8 (32% identical), GJA9 (31% identical), GJA4 (30% identical), GJA5 (29% identical), GJA10 (29% identical), GJA1 (28% identical), GJD2 (28% identical), GJC3 (27% identical), GJD3 (24% identical), GJB1 (23% identical), and 8 more.
Diseases named in the same sentence as GJC1 in open-access papers:
GJC1 is named in the same sentence as 60 diseases in open-access papers, as found by Europe PMC text mining. Sharing a sentence is not in itself a finding about the gene and the disease. The quoted sentences say what the papers report.
colorectal cancer (6 papers, 2014 to 2024). A primary or metastatic malignant neoplasm that affects the colon or rectum. "One study revealed through DNA methylation analysis that GJC1 was silenced by promoter hypermethylation in colorectal cancer." (PMID 39199296, 2024). "GJC1 methylation was correlated with BRAF mutations and proximal tumor location in colorectal cancer." (PMID 39199296, 2024). "Furthermore, DNA hypermethylation of the promoter region of GJC1 (CTC‐296K1.4), encoding connexin 45, is an important mechanism in silencing gene expression in colorectal cancer." (PMID 34816620, 2022).
Arrhythmia (5 papers, 2023 to 2026). Any cardiac rhythm other than the normal sinus rhythm. "Conversely, it was seen that mutations in Gjc1 could predispose people to congenital heart disease (CHD) and arrhythmias." (PMID 39329756, 2024).
diabetes (4 papers, 2012 to 2024). "Therefore, targeting GJC1 could be helpful for preventing diabetes-associated liver cancer." (PMID 39199296, 2024). "In a study bridging these areas, Cx45 (GJC1) was implicated in a potential connection between liver cancer and diabetes." (PMID 36077565, 2022). "Notably, patients with both liver cancer and diabetes presented significantly higher levels of global O-GlcNAcylation and expression of APA1 and GJC1 than did patients with just diabetes." (PMID 39199296, 2024).
atrial fibrillation (3 papers, 2021 to 2025). A disorder characterized by an electrocardiographic finding of a supraventricular arrhythmia characterized by the replacement of consistent P waves by rapid oscillations or fibrillatory waves that vary in size, shape and timing and are accompanied by an irregular ventricular response. "The WMH TWAS also identified genes associated with AD (ARMS2), atrial fibrillation (NEURL and GJC1), innate immunity (EFTUD2), and apoptosis and neurodevelopment (PDCD7, FBXO31, and ClpX)." (PMID 40141087, 2025).
liver cancer (3 papers, 2022 to 2024). An epithelial or non-epithelial malignant neoplasm that arises from the liver. "GJC1 was identified as a proto-oncoprotein that can enhance the proliferative capacity of liver cancer cells under high-glucose conditions." (PMID 39199296, 2024). "The zinc finger protein APA1 underwent O-GlcNAcylation in liver cancer cells, a step that is critical for the HG-induced binding of APA1 to the GJC1 promoter." (PMID 39199296, 2024).
lymphedema (3 papers, 2024 to 2025). Excess fluid collection in tissues, causing swelling. "Unfortunately, there are no reports of human lymphedema associated with Cx45 (GJC1) mutations." (PMID 40766782, 2025). "Finally, although there are no published reports of human lymphedema associated with mutations in Cx45 (GJC1), this Cx is critically important for a number of other physiological systems, most notably for the conduction of electrical signals in the developing heart." (PMID 39074069, 2024).
atrioventricular block (2 papers, 2022 to 2025). A heart block that is initiated in the atrioventricular node. "In a human study, a loss-of-function mutation in GJC1, R75H, was identified in two unrelated families with progressive atrial conduction system defects, including atrioventricular block (AVB) and atrial standstill." (PMID 35453689, 2022).
glioma (2 papers, 2017 to 2024). A benign or malignant brain and spinal cord tumor that arises from glial cells (astrocytes, oligodendrocytes, ependymal cells). "GJC1 holds promise as a valuable marker for identifying gliomas linked with a less favorable prognosis." (PMID 39360264, 2024). "In summary, we systematically investigated the influence of clinicopathological features, molecular subclasses, and prognosis of gliomas on GJC1 expression patterns." (PMID 39360264, 2024). "In this study, we performed a comprehensive analysis of GJC1 expression profiles across various glioma subtypes using data from the Chinese Glioma Genome Atlas (CGGA) and The Cancer Genome Atlas (TCGA) were used." (PMID 39360264, 2024). "Our investigation revealed significant overexpression of GJC1 in glioma, which demonstrated a compelling correlation with disease progression." (PMID 39360264, 2024). "The GO and KEGG enrichment analyses provided functional insights into the role of GJC1 in glioma pathogenesis." (PMID 39360264, 2024). "Further studies are warranted to investigate GJC1 as a novel biomarker or therapeutic mediator in gliomas or other tumor types." (PMID 39360264, 2024). "In this study, we observed distinct clinical and pathological characteristics among patients with glioma with different levels of GJC1 expression." (PMID 39360264, 2024). "We then conducted Kaplan–Meier analyses based on the CGGA and TCGA databases to explore the prognostic prediction value of GJC1 in patients with glioma." (PMID 39360264, 2024). "The strong correlation between GJC1 and key cell-cycle proteins underscores its pivotal role in the dysregulated cell cycle observed in glioma." (PMID 39360264, 2024). "In this study, GJC1 expression was investigated in low-grade gliomas and glioblastoma samples from the TCGA and CGGA datasets." (PMID 39360264, 2024). "Our study aimed to clarify potential correlations between GJC1 expression levels, clinicopathological characteristics, and overall survival (OS) among patients with glioma." (PMID 39360264, 2024). "GJC1 enrichment was observed in classical and mesenchymal subtypes within the TCGA glioma subtype group." (PMID 39360264, 2024). "GSVA revealed a strong correlation between GJC1 expression and gene sets and pathways related to cell-cycle regulation and mitosis in glioma." (PMID 39360264, 2024). "This study presents evidence demonstrating that abnormal overexpression of GJC1 independently contributes to a poorer prognosis for gliomas." (PMID 39360264, 2024). "Clinically, elevated GJC1 expression emerged as an independent indicator of a poor prognosis for individuals with glioma, offering a valuable avenue for its utilization as a prognostic biomarker to predict patient OS." (PMID 39360264, 2024). "This study investigated the predictive potential of GJC1 in gliomas and explored its relationship with the cell cycle." (PMID 39360264, 2024). "GJC1 identification as a prognostic marker for glioma, particularly its enrichment in the cell-cycle pathway as revealed through KEGG and GO analyses, provides valuable insights into the molecular mechanisms underlying glioma progression." (PMID 39360264, 2024). "The area under the curve for GJC1 in the glioma cohort consistently exceeded 68%." (PMID 39360264, 2024). "Therefore, experimental validation of GJC1 expression and function in glioma samples and cell lines is necessary to confirm our results." (PMID 39360264, 2024). "We identified GJC1 as a groundbreaking oncogenic factor in glioma." (PMID 39360264, 2024). "Additionally, the TCGA classical subtype of glioma cells exhibited more GJC1 expression than the other subgroups." (PMID 39360264, 2024). "We further investigated the role of GJC1 in gliomas using GSVA." (PMID 39360264, 2024).
glioma (continued). "Our findings provided new insights into the intricate interactions between GJC1 and glioma cell-cycle mechanisms and DNA damage response and offer the possibility of further investigating the potential of GJC1 as a therapeutic target for glioma." (PMID 39360264, 2024). "Such negative correlations did not appear in the analysis of the CGGA database; however, this suggested that GJC1 might also be involved in the regulation of DNA damage pathways in glioma." (PMID 39360264, 2024). "GJC1 emerged as an independent prognostic factor for overall survival in glioma." (PMID 39360264, 2024). "GSVA unveiled potential mechanisms by which GJC1 may impact cell-cycle regulation in glioma." (PMID 39360264, 2024). "To investigate the biological functions of GJC1 in gliomas, we conducted Pearson correlation analysis on glioma transcriptome data from TCGA and CGGA databases to identify genes most strongly correlated with GJC1 (|R| > 0.5, p < 0.05)." (PMID 39360264, 2024). "Consequently, GJC1 may be used to predict glioma prognosis and has potential therapeutic value." (PMID 39360264, 2024). "Glioma samples from the CGGA and TCGA datasets were categorized according to the WHO 2021 classification of gliomas, and GJC1 expression was compared between each group." (PMID 39360264, 2024). "In single-cell subgroup analysis, GJC1 expression was higher in glioma tissues compared to other non-neuronal cells." (PMID 39360264, 2024). "Additionally, GJC1 was negatively correlated with hallmark_kras_signaling_dn, which indicated a potential mechanism for suppressing KRAS signaling in glioma, possibly contributing to tumor suppression or influencing therapeutic response." (PMID 39360264, 2024). "To further investigate how GJC1 is involved in cell proliferation pathways and glioma subtypes, we conducted GSVA analysis on non-neuronal cell proliferation across the four Glioma Transcriptome Subtypes." (PMID 39360264, 2024). "The differential expression of GJC1 in gliomas with various pathological features and in different non-neuronal cell groups was analyzed." (PMID 39360264, 2024). "Additionally, a notable enrichment of GJC1 expression was observed in glioma samples with wild-type IDH and 1p/19q non-codeletion." (PMID 39360264, 2024). "GJC1 expression was enriched in high-grade gliomas and 1p/19q non-codeletion gliomas." (PMID 39360264, 2024). "Additionally, we scrutinized GJC1 expression at the single-cell level across distinct glioma subgroups and different non-neuronal cells." (PMID 39360264, 2024). "To determine which non-neuronal cell type GJC1 might be regulating in gliomas, we further analyzed GJC1 expression from a single-cell perspective to elucidate its role in gliomas." (PMID 39360264, 2024). "Additionally, through the analysis of public scRNA-seq datasets (GSE131928), we further confirmed that elevated GJC1 expression was predominantly enriched in glioma tumor cells compared with other non-neuronal cells." (PMID 39360264, 2024).
Sepsis (2 papers, 2020 to 2025). Sepsis is defined as life-threatening organ dysfunction caused by a dysregulated host response to infection. "Of the 317 sepsis-associated genes regulated by these DEMs, five (HIP1, GJC1, MDM4, IL6R, and ERC1) were designated as hub genes based on their degrees and other centrality measures (degree, betweenness, and closeness) from the significant modules." (PMID 33182754, 2020).
cystitis (1 paper, 2017). Inflammation of the urinary bladder. "In the down-regulated candidate genes, GJC1 and TICAM2 demonstrated the most statistically significant association with cystitis (rawP = 6.77e-05, adjP = 3.40e-04)." (PMID 28899343, 2017).
neuroblastoma (1 paper, 2021). Neuroblastoma (NB) is the most common solid, extracranial childhood tumor. "Three of those genes (CBX2, GJC1, LIMD2) are encoded on 17q, a chromosomal region invariably gained in high-risk neuroblastoma." (PMID 34638267, 2021).
tumor (11 papers, 2013 to 2024). "We analyzed the biological processes and markers associated with GJC1 in tumor cells and further performed drug correlation analysis." (PMID 39360264, 2024). "Previously, we identified Alu hyper-editing of Gap junction gamma-1 (GJC1) protein in relapsed tumour cell-lines after immunotherapy." (PMID 35993275, 2022). "Furthermore, Alu editing in GJC1 is reported as clinically relevant, showing differential editing levels across tumor subtypes and tumor stages and correlating with patients’ overall survival rates." (PMID 33445472, 2021). "Of further interest, we found a KEOPS complex member (gm6890), implicated in homologous double-strand break repair and telomere maintenance, to be strongly upregulated during tumor formation, as well as the checkpoint adaptor Claspin (CLSPN) and three chromosome 17q loci CBX2, GJC1 and LIMD2." (PMID 34638267, 2021).
cancer (4 papers, 2023 to 2025). A tumor composed of atypical neoplastic, often pleomorphic cells that invade other tissues. "Furthermore, we observed a positive correlation between GJC1 expression and sensitivity to several anti-cancer drugs." (PMID 39360264, 2024). "Finally, a significant correlation was observed between GJC1 expression and the sensitivity of multiple anti-cancer drugs." (PMID 39360264, 2024).
cardiac disease (3 papers, 2017 to 2022). "In addition to GJA1 and GJA5, one mutation (p.Arg75His) in the GJC1 (encoding Cx45) gene has been reported to be related to heart disease to date." (PMID 35457072, 2022).
cardiovascular diseases (2 papers, 2019 to 2020). "Cardiovascular disorders are the most common phenotypes associated with GJC1." (PMID 33126609, 2020).
infection (2 papers, 2013 to 2017). The state of being infected such as from the introduction of a foreign agent such as serum, vaccine, antigenic substance or organism. "Gene profiling of T. cruzi-infected cardiomyocytes revealed suppression of GJA1 and GJC1 genes, which encode for Cx43 and Cx45 proteins, respectively, at 48 hours after infection." (PMID 24236292, 2013).
peripheral nervous system disease (1 paper, 2023). "A number of these, including connexin 26 (Cx26)/GJB2, Cx29/Cx31.3/GJC3, Cx30/GJB6, Cx32/GJB1, Cx36/GJD2, Cx43/GJA1, Cx45/GJC1 and Cx47/GJC2 are expressed in the central and/or peripheral nervous system and mutations in a number of these cause central and/or peripheral nervous system disease." (PMID 37189458, 2023).
GJC1 also shares sentences with these, for which no sentence is quoted: cardiomyopathy (4 papers); congenital heart disease (3); dysferlinopathy (3); heart failure (3); Hypertension (3); endotoxemia (2); familial atrial fibrillation (2); ischemia (2); melanoma (2); myocardial infarction (2); oral squamous cell carcinoma (2); sarcoma (2); acute myeloid leukemia (1); atrial standstill (1); bladder (1); bladder pain syndrome (1); Bradycardia (1); cardiac arrhythmia (1); follicular lymphoma (1); glaucoma (1); glioblastoma (1); leukemia (1); myeloid leukemia (1); myocarditis (1); nephrotic syndrome (1); neurodegenerative disease (1); overactive bladder (1); preeclampsia (1); pulmonary stenosis (1); Renal artery stenosis (1).
A further 13 diseases each share a sentence with GJC1 in 1 paper.